SLC1A5 (solute carrier family 1 member 5)
Diseases named in the same sentence as SLC1A5 in open-access papers (continued):
Sharing a sentence is not in itself a finding about the gene and the disease.
hepatocellular carcinoma (35 papers, 2014 to 2025). A malignant tumor that arises from hepatocytes. "Furthermore, genetic variants in the SLC1A5 gene have also been implicated in hepatocellular carcinoma prognosis, with stage I patients carrying the rs2070246 TT genotype showing higher overall survival (OS) than carriers of CC genotype." (PMID 33429909, 2021). "Early studies on LC using a human hepatocellular carcinoma cell line (Hep G2 cells) revealed that both slc1a5 promoter activity and the protein expression of ASCT2 were dependent on the presence of Gln." (PMID 39308523, 2024). "To clarify the expression of SLC1A5, we selected three hepatocellular carcinoma cells and normal hepatic epithelial cells to perform qPCR experiments." (PMID 37818360, 2023). "The results indicated that the proliferation, migration and invasion of hepatocellular carcinoma cells were significantly reduced after knockdown of SLC1A5." (PMID 37818360, 2023). "Via the modulation of SLC1A5 and the mTORC1 signaling pathway, the discoidin domain receptor 1 promotes the progression of hepatocellular carcinoma." (PMID 36902506, 2023). "Subsequently, we used siRNA to knock down SLC1A5 in hepatocellular carcinoma cells and found that cell proliferation, migration and invasion were diminished." (PMID 37818360, 2023). "In hepatocellular carcinoma, we observed that the expression level of SLC1A5 was dramatically up-regulated, while the ability of hepatocellular carcinoma cells to proliferate was significantly down-regulated after SLC1A5 expression was silenced using siRNA." (PMID 37818360, 2023). "It is now well established that SLC1A5 is upregulated and promotes cancer development in multiple cancers, such as hepatocellular carcinoma (HCC), non-small-cell lung cancer (NSCLC), and gastric cancer (GC)." (PMID 35419359, 2022). "For example, miR-122 has been reported to modulate the expression of SLC1A5 in hepatocellular carcinoma." (PMID 34573287, 2021). "Correlation of SLC1A5 mRNA expression and prognosis in hepatocellular carcinoma (HCC) with different clinicopathological factors in Kaplan-Meier plotter." (PMID 34367941, 2021). "Similarly, in human hepatoma cells, SLC1A5/ASCT2 silencing inhibits MTORC1, which in turn signals to the translational machinery." (PMID 37614038, 2024). "Next, a literature search was conducted to focus on proteins specifically associated with liver disease in general, which selected 20 proteins, seven of which (i.e., CEP55, CLIC1, EPS15L1, G6PD, KIF11, SLC1A5, and TK1) were found to be specifically associated with hepatocellular carcinoma." (PMID 37627157, 2023). "Subsequently, we found that after culturing macrophages using conditioned medium from hepatocellular carcinoma cells with knockdown of SLC1A5, the expression of M2-type macrophage marker molecules was decreased, and the expression levels of CD206 and ARG1 were markedly down-regulated in macrophages." (PMID 37818360, 2023). "The results suggested that the malignancy of hepatocellular carcinoma cells increased when the ligand agonized SLC1A5, and targeting SLC1A5 could alleviate tumor progression in hepatocellular carcinoma patients in the future." (PMID 37818360, 2023). "This experimental phenomenon suggests that the expression of SLC1A5 by hepatocellular carcinoma cells may have an effect on the immune microenvironment." (PMID 37818360, 2023). "The ferroptosis-related gene SLC1A5 correlates with the progression of HBV-related hepatocellular carcinoma (HCC), suggesting its potential as an excellent novel prognostic indicator." (PMID 39600338, 2024). "SLC1A5 expression was significantly higher in several types of cancers, including hepatocellular carcinoma (HCC), compared with corresponding normal tissues." (PMID 34367941, 2021).
hepatocellular carcinoma (continued). "It is reported that in the prognosis model of hepatocellular carcinoma, the genes (NFS1, CISD1, ACSL3, NQO1, SLC7A11, GPX4) that can protect hepatocytes with ferroptosis and the genes (ACACA, CARS, G6PD, SLC1A5) that induce ferroptosis are all up-regulated in HCC, and are related to poor prognosis." (PMID 36387286, 2022). "SLC1A5 expression correlated positively with immune cells, such as tumor-infiltrating B cells, CD4+ T in hepatocellular carcinoma, and lower-grade glioma." (PMID 35359663, 2022). "In hepatocellular carcinoma cells (HCC), over-expression of the Solute Carrier Family 1 Member 5 (SLC1A5) results in a poor prognosis." (PMID 34885950, 2021). "Then, using Liver Hepatocellular Carcinoma database of The Cancer Genome Atlas (TCGA-LIHC), the authors demonstrated an inverse correlation between a high expression of GLS and SLC1A5 with low levels of miR-122 and related this to poor prognosis in high-grade primary HCC tumors." (PMID 32326003, 2020). "We found that the expression level of SLC1A5 was higher in all hepatocellular carcinoma cells than in normal hepatic epithelial cells, with the higher expression level in Huh7 and SNU398 cells." (PMID 37818360, 2023). "created a novel Hepatocellular Carcinoma prediction model that integrates 7 GlnMgs, including SLC1A5, GAPDH, SLC38A1, SLC38A7, FTCD, MTHFS, and GOT2 might be utilized to predict prognosis in HCC." (PMID 37377916, 2023).
glioma (34 papers, 2010 to 2025). A benign or malignant brain and spinal cord tumor that arises from glial cells (astrocytes, oligodendrocytes, ependymal cells). "Specifically, SLC1A5 expression was positively associated with the infiltration of CAFs, monocytes, and M2 macrophages in glioma and negatively associated with the infiltration of Tfh cells and MDSCs." (PMID 37566748, 2023). "After screening and validation, we revealed that SLC1A5 mediated the malignant phenotypes by affecting the ferroptosis state, the infiltration and polarization of tumor-associated macrophages (TAMs) in glioma." (PMID 36566214, 2022). "Considering that SLC1A5 affected the proliferation and invasion of glioma cells in vitro and the susceptibility of U87 cells to tumor formation in the brain of nude mice, we transplanted the transfected U87 cells into the brains of BALB/c nude mice respectively." (PMID 36566214, 2022). "Biological experiments also verified that SLC1A5 could affect the infiltration and polarization of immune tumor-associated macrophages in tumor samples and glioma cells." (PMID 36566214, 2022). "Analysis of glioma samples reveals that the level of COL1 is correlated with histopathological grade of glioma and the expression of SLC1A5." (PMID 37997289, 2024). "Our study confirmed that Akt up‐regulated SLC1A5, which promoted the self‐renewal of glioma stem cells." (PMID 37997289, 2024). "Liying Han and colleagues reported a significant increase in SLC1A5 expression in glioblastoma tissues compared to low-grade gliomas." (PMID 38317842, 2024). "For instance, SLC1A5 enhances malignant phenotypes through modulating ferroptosis status and immune microenvironment in glioma." (PMID 39193375, 2024). "Glutathione depletion with BSO blocked the effect of SLC1A5 on the self‐renewal of glioma stem cells." (PMID 37997289, 2024). "Building upon the evidence of the prognostic significance of SLC1A5 in gliomas, we further investigated its functional implications through GSEA." (PMID 37566748, 2023). "We first evaluated differential expression of SLC1A5 in pancancer and normal tissues and further investigated the RNA expression level of SLC1A5 in clinical glioma samples." (PMID 37566748, 2023). "ASCT2 (Slc1a5), the key glutamine importer, is strongly expressed in a rat astrocytoma-derived glioma model." (PMID 37108511, 2023). "After further study, we found that SLC1A5 is a suppressor of ferroptosis in glioma, and knockdown of SLC1A5 can downregulate the expression of GPX4." (PMID 37566748, 2023). "To study the effect of SLC1A5 knockdown on ferroptosis in glioma cells, we evaluated the level of ferroptosis in cells by measuring ferroptosis indexes with kits." (PMID 37566748, 2023). "Using the TIMER online database, we discovered a significant correlation between SLC1A5 expression and immune cell infiltration in glioma." (PMID 37566748, 2023). "In the Glioma_GSE131928_Smartseq2 dataset, which contains 7,930 cells from 28 glioma patients, SLC1A5 was highly expressed in malignant cells and monocytes/macrophages in the glioma microenvironment." (PMID 37566748, 2023). "Our results also showed that SLC1A5 knockdown inhibited the proliferation and migration of glioma cells in vitro." (PMID 37566748, 2023). "Next, we collected glioma samples and performed RT‒qPCR to detect the expression of SLC1A5 and found that the expression of SLC1A5 in glioma tissues was higher than that in adjacent tissues." (PMID 37566748, 2023). "Upon further investigation, we found that SLC1A5 is a suppressor of ferroptosis in glioma, and SLC1A5 knockdown inhibited the proliferation and migration of glioma cells in vitro." (PMID 37566748, 2023). "Many lines of evidence suggested that the glutamine transporter (ASCT2/SLC1A5) was upregulated in C6 glioma cells." (PMID 37198251, 2023). "In our study, we demonstrated that SLC1A5 was an oncogene in glioma, and overexpressed in glioblastoma." (PMID 36566214, 2022).
glioma (continued). "To further detect the effects of SLC1A5 knockdown in glioma cells on macrophages, we co-cultured THP-1 derived macrophages (PMA, 5 nM, 48 h) with shCtrl and sh-SLC1A5 glioma cells." (PMID 36566214, 2022). "The transwell assay showed that the migrated cells of THP-1 derived macrophages co-cultured with sh-SLC1A5 glioma cells were significantly reduced." (PMID 36566214, 2022). "HE staining demonstrated that the tumor size in SLC1A5 group was significantly larger than that in vector group, and glioma in sh-SLC1A5 group, by contrast, developed more slowly than that in shCtrl group." (PMID 36566214, 2022). "On the contrary, SLC1A5 overexpression in T98G cells significantly promoted the cell viability, proliferation and invasion of glioma cells." (PMID 36566214, 2022). "Our results showed that the expression of SLC1A5 was significantly upregulated in glioblastoma tissues compared with the low-grade gliomas." (PMID 36566214, 2022). "To investigate the function of SLC1A5 in vitro, we first examined the protein and mRNA expression of SLC1A5 in human normal astrocyte cell line HA1800 and different glioma cell lines and noticed that the expression of SLC1A5 was higher in the glioma cells." (PMID 36566214, 2022). "Glioma patients in the SLC1A5 high-expression group had higher immune scores and lower tumor purity." (PMID 36566214, 2022). "Flow cytometry showed that when the THP-1 derived macrophages were co-cultured with the sh-SLC1A5 glioma cells, the ratio of M2-like macrophages (CD11b+CD206+) were decreased." (PMID 36566214, 2022). "To investigate the function of SLC1A5 in glioma cells, we selected the T98G cell line for the following cytological experiments due to its significant expression of SLC1A5." (PMID 36566214, 2022). "The expression of SLC38A1, another glutamine transporter on the cell membrane, was less different in these cell lines, suggesting SLC1A5 was the main glutamine transporter in glioma cells." (PMID 36566214, 2022). "Correspondingly, lncRNA-XIST knockdown in glioma promotes ROS production and apoptosis and inhibits cell proliferation in SLC1A5/miR-137 dependent fashion, which can be reversed by cell supplementation with N-acetyl-L-Cysteine (NAC), a scavenger of ROS." (PMID 33401748, 2021). "Gene expression profiling has shown an upregulation of the glutamine importer ASCT2 (SLC1A5) compared to low grade gliomas, and glutamine deprivation has slowed GBM tumor growth in some in vitro studies." (PMID 34277624, 2021). "Several human glioma cell lines are shown to upregulate expression of ASCT2 (SLC1A5), the principal glutamine importer, which drives rapid glutamine uptake in tumor cells." (PMID 31652923, 2019). "Notably, the knockdown of SLC1A5 significantly curtailed the proliferation and invasion of glioma cells." (PMID 38317842, 2024). "SLC1A5, another member of the SLC1A family, has been implicated in the regulation of ferroptosis and immune response in gliomas and could serve as a prognostic biomarker for gliomas and a potential therapeutic target." (PMID 39218897, 2024). "Additionally, the glutamine transporter protein SLC1A5 (ASCT2) is also overexpressed in human glioblastoma cell lines and rat C6 glioma cells." (PMID 39051546, 2024). "Although bioinformatics analysis has revealed a correlation between SLC1A5 expression and the prognosis of glioma patients, the precise role of SLC1A5 and its relationship with the immune status of glioma patients and immunotherapy remain unclear." (PMID 37566748, 2023). "In glioma cells, SLC1A5 could affect the infiltration and polarization of immune tumor-associated macrophages." (PMID 36902506, 2023). "Finally, in vitro experiments verified that SLC1A5 participates in ferroptosis of glioma cells to regulate tumor progression." (PMID 37566748, 2023). "Inhibition of SLC1A5 by genetic interference or chemical drugs could suppress the growth of glioma in vitro and in vivo." (PMID 36566214, 2022).
glioma (continued). "The goal of our study is to establish a ferroptosis-related prognostic model that could apply to glioma prognostic prediction and verify the molecular mechanism of the FRG, SLC1A5, in glioma." (PMID 36566214, 2022). "In addition, it was reported that direct inhibition of SLC1A5 by miR-137 enhances glioma cell oxidative stress and triggers lipid peroxidation, which eventually induces tumor cell death." (PMID 35965517, 2022). "In our study, transcriptome and proteome sequencing results and bioinformatic analysis in TCGA cohort showed that differential expression of SLC1A5 could affect immune cell infiltration and immune-related pathways in glioma cells." (PMID 36566214, 2022). "However, the concrete mechanism of how the expression of SLC1A5 affects the immune response in glioma needs further investigation." (PMID 36566214, 2022). "Accordingly, we proposed that SLC1A5 could play a role in the progression and clinical therapy of glioma." (PMID 36566214, 2022). "The combination of ferroptosis inducer with the inhibition of SLC1A5 could further increase the level of oxidative stress in glioma." (PMID 36566214, 2022). "The combination of ferroptosis inducer with the inhibition of SLC1A5 could further inhibit glioma growth." (PMID 36566214, 2022). "The high amount of glutamine transported by SLC1A5 could provide excessive energy for glioma cell growth and proliferation, through TCA cycle as well as oxidative phosphorylation, under Warburg effect, in which tumor metabolism prefers anaerobic glycolysis." (PMID 36566214, 2022). "The qPCR and WB results demonstrated the expression of SLC1A5 was increased in high-grade gliomas." (PMID 36566214, 2022). "Knockdown of lncRNA-XIST reduces SLC1A5 levels and inhibits tumorigenesis of glioma cells in vivo." (PMID 33401748, 2021). "Thus, we further investigated whether SLC1A5 inhibitor could sensitize glioma to immunotherapy in vivo." (PMID 36566214, 2022). "In addition, SLC1A5 knockdown could significantly inhibit glioma cell proliferation and invasion, and reduce the sensitivity of ferroptosis via the GPX4-dependent pathway." (PMID 36566214, 2022). "However, the effect of SLC1A5 and the relationship between SLC1A5 and immune state in glioma remains unclear." (PMID 36566214, 2022). "However, in our study, we found that SLC1A5 was the suppressor of ferroptosis in glioma and overexpression of SLC1A5 could increase the expression of GPX4." (PMID 36566214, 2022). "Besides, SLC1A5 in the model could regulate the proliferation, invasion, ferroptosis and immune state in glioma, and be applied as a prognostic biomarker and potential therapeutic target for glioma." (PMID 36566214, 2022). "Similarly, survival probability in hepatocellular carcinoma was reliably predicted by a glioma prediction model (ACSL3, ACSL6, ACACA, G6PD, SLC1A5, SLC7A11 and VDAC2) and by a risk model with a strong overlap with the genes in the glioma models (G6PD, HMOX1, LOX, SLC7A11, STMN1/Stathmin 1)." (PMID 34926298, 2021). "For instance, in U87-MG glioma and A549 cells, alanine uptake is facilitated by SNAT1, SNAT2, SNAT5, SLC6A15 (B0AT2), SLC7A6 (y+LAT2), SLC1A4 (ASCT1), and SLC1A5 (ASCT2), and many of these transporters are also involved in glutamine transport." (PMID 40716744, 2025). "Furthermore, SLC1A5, one of the FRGs in prognostic model, enhances the malignancy of gliomas, modulates the tumor ferroptosis status and immune microenvironment, and may be a potential prognostic biomarker and promising candidate target for glioma treatment." (PMID 36566214, 2022). "Therefore, we hypothesized that SLC1A5 might function in glioma progression and clinical treatment." (PMID 36566214, 2022). "Our findings showed the prognostic value of SLC1A5 in HCC and lower-grade glioma (LGG) and provided novel insights into the correlation of and mechanism active between SLC1A5 expression and tumor immunity." (PMID 34367941, 2021).
glioma (continued). "The results showed that SLC1A5 was up-regulated in gliomas compared with normal brain tissues in both mRNA and protein levels, and HSPB1 was also overexpressed in glioma samples." (PMID 34726238, 2021). "Furthermore, we explored the mRNA expression levels of SLC1A5 and HSPB1 in the GEPIA website and the protein expression levels using clinical samples between normal brain tissues and gliomas." (PMID 34726238, 2021). "Moreover, SLC1A5 expression correlated positively with the numbers of tumor-infiltrating B cells, CD4+ T and CD8+ T cells, macrophages, neutrophils, and dendritic cells in HCC and in lower-grade glioma (LGG)." (PMID 34367941, 2021). "However, a comprehensive characterization of SLC1A5 had not yet been explored in glioma." (PMID 36566214, 2022).